CD4 (CD4 molecule)
Diseases named in the same sentence as CD4 in open-access papers (continued):
Sharing a sentence is not in itself a finding about the gene and the disease.
Arthritis (continued). "MHC IIΔ/Δ and NRG mice show clearly reduced foot swelling when compared with C57BL/6 mice (C57BL/6, MHC IIΔ/Δ and NRG), consistent with previous data showing that CD4 T cells are important for driving CHIKV arthritis." (PMID 25474568, 2014). "Flowcytometry analysis of the IL-22R1 on CD4+ cells also showed that the expression of this subunit is increased with the onset of arthritis, confirming the findings of real-time PCR studies." (PMID 24676270, 2014). "At 25 days following the onset of arthritis, the percent frequencies of Th17 (CD4+IL-17+) and Treg (CD4+Foxp3+) cells among CD4+T cells isolated from the spleen of CIA mice treated with or without CD11b+DCs were determined." (PMID 25405209, 2014). "ATRA treatment down-regulated the expression of RANKL a key osteoclastogenic molecule expressed in CD4+ T-cells and fibroblast-like synoviocytes and osteoclast formation in arthritis joints was reduced." (PMID 23970886, 2013). "It was rather surprising that IL-17 KO mice showed hyporesponsiveness to K/BxN serum transfer, since this means that IL-17 from cells other than CD4+ T cells are important for arthritis development." (PMID 23671588, 2013). "Following immunization with this Hsp70 peptide responding CD4+CD25+ spleen lymphocytes had a high capacity to suppress disease in an experimental model of arthritis upon adoptive transfer." (PMID 23970886, 2013). "Depletion was confirmed by flow cytometry, and although a small fraction of CD4+ T cells remained on day -7, this was not sufficient to induce an inflammatory response, and by day 9 after DTH-arthritis induction, all CD4+ T cells were depleted from the system." (PMID 22676339, 2012). "Using intracellular cytokine staining it was demonstrated that the IL-10-/- B cell mice with arthritis had an increased CD4+ IFNγ producing population." (PMID 22315945, 2012). "The fact that GPI peptide-induced arthritis is T cell dependent, especially IL-17-producing CD4+ T cells, we also examined the effects of α-GalCer on antigen-specific CD4+ T cells." (PMID 23251456, 2012). "In contrast to these studies, α-GalCer suppressed both Th1 and Th17 CD4+ T cells in GPI peptide-induced arthritis." (PMID 23251456, 2012). "In conclusion, the present study demonstrated that α-GalCer significantly suppressed GPI peptide-induced arthritis through the suppression of antigen-specific CD4+ T cells." (PMID 23251456, 2012). "The analysis of the CIA symptoms in the recipient mice showed that the adoptive transfer of CD4+CD25+ cells significantly decreased the arthritis score and incidence from day 6 to 15 of onset, compared with the PBS group." (PMID 22848374, 2012). "We have verified that DTH-arthritis induction is dependent on CD4+ T cells and anti-CII antibody-mediated tissue damage of the joint." (PMID 22676339, 2012). "GPI-induced arthritis is a newer and closer model of human RA with regard to its dependency on CD4+ T cells and reactivity to biological treatments such as blockade of IL-6 and TNF-α, which are well known to be effective in human RA." (PMID 23251456, 2012). "DTH-arthritis is dependent on CD4+ cells for induction and can be successfully treated with TNFα-blocking biologics and dexamethasone." (PMID 22676339, 2012). "Higher percentage of IL-17-producing CD4+ T cells were determined in CIA mice in early arthritis (2.5% and 4.3%, for the first and second sacrifice, resp." (PMID 22028728, 2012). "GPI-induced arthritis is considered to be a closer model of human RA than CIA with regard to its dependency on CD4+ T cells and response to biological agents, such as anti-TNF-α and anti-IL-6 receptor antibody." (PMID 23251456, 2012). "Polymerized-Type I Collagen and methotrexate/Polymerized Collagen treatments had a sustained effect in early and established arthritis model until the second sacrifice (follow up) on the percentage of IL-17A-producing CD4+ T." (PMID 22028728, 2012).
Arthritis (continued). "IL-17-producing CD4+ T cells contribute to severe synovitis, pannus formation, joint destruction in arthritis joints and autoimmune inflammation." (PMID 22028728, 2012). "α-GalCer significantly suppressed GPI peptide-induced arthritis through the suppression of GPI-specific CD4+ T cells." (PMID 23251456, 2012). "Depletion of CD4+CD25+ T cells aggravated CIA, whereas transferring CD4+CD25+ cells to a disease-bearing animal ameliorated arthritis." (PMID 22192790, 2011). "The response of CD4 positive T cells against peptide antigens derived from the injected type II collagen is central for the development of murine arthritis." (PMID 21858160, 2011). "CD4+ T cells play an important role in disease progression in the collagen-induced arthritis model, as evidenced by the fact that anti-CD4 treatment suppresses the onset of arthritis." (PMID 21483764, 2011). "In other diseases, like the arthritis mouse model, orally administered type II collagen was shown to induce CD4+CD25+Foxp3+ regulatory cells by IDO expressing CD11c+ DCs in intestinal Peyer's patches in the treatment of arthritis." (PMID 21765853, 2011). "In various experimental arthritis models, Hsp(-peptides) were shown to have a capacity to down modulate arthritis, which seems to be mediated by the induction of Hsp-specific regulatory CD4+ T-cells." (PMID 22073184, 2011). "Given the fact that non-depleting anti-CD4 treatment prevents the onset of autoimmune arthritis, we tested the effectiveness of a similar course of anti-CD4 for the treatment of established arthritis in SKG mice." (PMID 20479941, 2010). "Indeed, in vivo treatment with the B22a1 antibody was efficient in depleting B22a1+CD4+ T cells, as only very few B22a1+ T cells could be identified in the spleen and lymph nodes by the end of the arthritis experiment and caused a delay in disease onset (P < 0.05)." (PMID 20682070, 2010). "Most significantly, the co-introduction of these molecules into CD4+ T cells resulted in their ability to significantly block the development of arthritis in a well-established murine model." (PMID 20384988, 2010). "In line with this, the frequency of IFNγ-producing CII-specific T cells among CD4+ T cells also peaked before onset of clinical arthritis and subsequently declined with progression of disease." (PMID 20682070, 2010). "Although CD4+ T cells, and its Th17 subset, are important in the pathogenesis of arthritis in SKG mice, other cell populations, such as B cells, participate in the disease as suggested by the production of RF in these animals." (PMID 20479941, 2010). "T-cell receptor transgenic mice, in which nearly all CD4+ T cells recognize a single peptide of type II collagen, were immunized with collagen and observed for development of arthritis for 4 weeks." (PMID 19706160, 2009). "Our previous report suggested that cross-reactivity of CD4+ T cells primed with hGPI325-339 to mGPI325-339 was critical for the development of arthritis." (PMID 19900268, 2009). "Anti-IL-7 antibody not only inhibited CD4+ T-cell proliferation (which was a requirement for the development of arthritis) but anti-IL-7 antibody administration also ameliorated arthritis severity." (PMID 20339519, 2009). "This is reminiscent of recent studies showing that lactic acid bacteria decrease the Th1-type CD4 responses to type II collagen in a mouse model of arthritis." (PMID 19300508, 2009). "We have also demonstrated that the major epitope of CD4+ T cells in GPI-induced arthritis was hGPI325-339, and immunization with the peptide induced severe polyarthritis (GPI peptide-induced arthritis)." (PMID 19900268, 2009). "Although the lymphadenopathy in MRL/lpr mice is due to accumulation of CD4-CD8-B220+ T cells, features of autoimmunity such as production of autoantibodies, arthritis, and sialadenitis depend mainly on CD4+ T cells." (PMID 17284325, 2007).
Arthritis (continued). "Like the CD4+ T cells from these animal models, IL-32β-producing CD4+ T cells exacerbated collagen-induced arthritis." (PMID 17078892, 2006). "The mice group to which the hIL-32β-transduced CD4+ T cells had been transferred developed arthritis earlier than the mock group of mice and showed significantly higher arthritis scores." (PMID 17078892, 2006). "In animal models of arthritis, the transfer of CD4+ T cells from SKG mice and IL-1Ra-deficient mice has evoked arthritis in the recipient mice." (PMID 17078892, 2006). "Analogous to the present observations, synovial fluid from patients with arthritis contained comparable numbers of CD4+ memory T cells expressing CLA, integrin α4β7 and CCR4 as peripheral blood." (PMID 16824229, 2006). "Beyond the 100% incidence of arthritis, another major advantage of the AIA model is that the time point of induction of arthritis is known, allowing manipulation of CD4+CD25+ Treg cell number in vivo at defined stages in the disease." (PMID 15743476, 2005). "Further support for the influence of CD4+CD25+ Treg cells on arthritis development came from the transfer experiments." (PMID 15743476, 2005). "We show here that CD134 can be used as a marker for recently activated CD4+ T cells with auto-aggressive potential in arthritis, and that anti-CD134 liposomes can be used to target drugs directly to these T cells." (PMID 15899047, 2005). "Previously, it has been shown that a CD4+ T cell clone (clone A2b), derived from a Lewis rat after Mt immunization and capable of transferring arthritis to naive rats, recognized a T cell epitope present in the 176–190 region of Mt HSP60 (Mt HSP60176–190)." (PMID 15899047, 2005). "Taken together, these data clearly demonstrate that CD4+CD25+ Treg cells regulate the severity of arthritis by limiting the cellular and humoral immune responses against the inducing antigen mBSA as well as some arthritis-related autoantigens." (PMID 15743476, 2005). "The exact role played by naturally occurring CD4+CD25+ Treg cells in the pathogenesis of arthritis remains controversial." (PMID 15743476, 2005). "Depletion of CD4+ T cells has a major influence during the priming phase of arthritis and suppressed the adoptive transfer of disease to severe combined immunodeficient mice using spleen cells from CII-immunized mice." (PMID 15535832, 2004). "SKG mice with NORA microbiota had an increase in gut Th17 cells and developed more severe arthritis than SKG mice with HC microbiota.SKG mouse spleen naive CD4+ T cells co-cultured with P. copri stimulated DC produce high levels of IL-17 in response to RA autoantigen RPL23A." (PMID 41574450, 2026). "However, the FOXP3 mRNA expression in isolated CD4+CD25+CD127dim/− T cells tended to be higher in the arthritis patients than in the HCs, with the highest expression levels in isolated cells of RA and SpA patients." (PMID 40806470, 2025). "The proportions of CX3CR1+CD4+ T cells positively correlated with arthritis activity in LORA." (PMID 39910629, 2025). "In addition, expanded senescent CD4+PD-1+T cells accelerated arthritis progression in CIA mice, indicating the key roles of these cells in the pathogenesis of RA." (PMID 40825269, 2025). "These mice develop an excess of CD4 and Th17 T lymphocytes and are prone to arthritis, whereas other mice with an intestinal microbiota composed only of Bacteroides fragilis show overrepresented regulatory T lymphocytes or Tregs and arthritis resistance." (PMID 40868558, 2025). "Notably, the ankle joint exhibited a markedly increased proportion of CD4+ Th cells in the context of arthritis, while the percentage of CD19+ B cells was reduced, and the number of macrophages and neutrophils was unaffected." (PMID 40755771, 2025). "In inflammatory states, lactate role is multifaceted, it may aggravate arthritis by diminishing glycolysis and augmenting lipogenesis via the restriction of CD4+T lymphocyte motility, thus perpetuating inflammation." (PMID 39325940, 2024).
Arthritis (continued). "CD4+T cells specific for citrullinated tenascin-C were the most frequently observed among the progressors, and their frequencies diminished during follow-up that is, closer to arthritis onset." (PMID 39557489, 2024). "In addition to improvements in arthritis, we evaluated CD4+T lymphocyte levels in patients treated with IL-2 and IL-2+TCZ after the corresponding regimen." (PMID 38711497, 2024). "Interestingly, there was a significant decrease of cit-TNC-specific CD4+T cells in the progressor group on arthritis onset (p<0.05)." (PMID 39557489, 2024). "In this study, we have explored the presence and phenotype of cit-specific autoreactive CD4+T cells in the development of RA during the period leading up to arthritis onset (the pre-RA phase) and compared this with group of at-risk individuals who have not (yet) progressed to disease." (PMID 39557489, 2024). "Intriguingly, the frequencies of cit-reactive CD4+T cells were lower in individuals who later progressed to arthritis, which might represent a process of homing of these cells from the circulation to the joint and/or joint-associated lymphoid tissue." (PMID 39557489, 2024). "Knockdown of TAp63 in SKG CD4+ T cells ameliorates arthritis." (PMID 37212280, 2023). "In addition, CD4+ T cells isolated from SKG mice induce arthritis if transferred to immunodeficient SCID mice." (PMID 37212280, 2023). "Under inflammatory conditions such as arthritis, the CD4+CD25+ Treg population is increased." (PMID 36477951, 2022). "Interestingly, several studies focussing on arthritis pathogenesis revealed that CD4+ T cells together with inflammatory and innate immune responses play a central role." (PMID 35544042, 2022). "Furthermore, studies have reported that in mouse models, dietary ω-3 fatty acids had been successfully used to reduce the severity of arthritis and atopic dermatitis by promoting the differentiation of CD4+ T cells into Tregs." (PMID 35296075, 2022). "To investigate whether exacerbated arthritis symptoms were caused by enhanced TNF-α expression in CD4 T cells upon SIGIRR deficiency, we examined cytokine production in memory CD4+ T cells upon antigen immunization." (PMID 36401167, 2022). "We established that these SKG GFPhi naive CD4 T cells were more arthritogenic than the GFPlo subset using an established adoptive transfer model in which SKG CD4 T cells are sufficient and necessary to cause arthritis in a lymphopenic host." (PMID 34923645, 2022). "Consistent with our findings, previous studies have shown that SOX4 is a critical transcription factor involved in the progression of multiple cancers, and it has also been found to be upregulated in mouse arthritis models and CD4 + T cells in the inflamed joints of RA patients." (PMID 36513634, 2022). "It was found that B29-induced CD4+CD25+Foxp3+ T cells could suppress arthritis in the proteoglycan-induced RA mice model both prophylactically and therapeutically, indicating these self-antigen-specific Treg cells could regulate immune disorder in vivo." (PMID 36248797, 2022). "To evaluate the role of T-bet in CD4 + T cells on the pathogenesis of arthritis, we generated T-bet conditional KO (cKO) mice by crossing CD4-Cre mice with T-betfl/fl mice (which selectively lose the T-bet gene in T cells), and compared the severity of CIA in T-betfl/fl control mice and cKO mice." (PMID 34462459, 2021). "Immunization of a specific peptide that is a major CD4+ T cell epitope of GPI could induce arthritis in DBA/1 mice (peptide GPI-induced arthritis; pGIA)." (PMID 34299252, 2021). "We then assessed the effects of Gsdmd on CD4+ T cell profiles after the induction of arthritis." (PMID 34548542, 2021). "Because RvD5 suppressed Th17 cell differentiation and facilitated Treg differentiation, inhibited CD4+ T cell proliferation and interfered with osteoclastogenesis, we hypothesized that RvD5 treatment might prevent arthritis progression in SKG mice." (PMID 34453072, 2021).
Arthritis (continued). "Since arthritis in mice with CIA results from a contribution by CD4+ T cells and B cells which may be suppressed by CD4+CD25+Foxp3+ Tregs, it was important to determine whether percentages of these cell populations were changed by 20S(OH)D3 treatment." (PMID 34276665, 2021). "In addition, the percentage of CD4+GranzB+CTLs was markedly higher in pSS patients with extraglandular manifestations including secondary interstitial lung disease, renal damage, arthritis, and autoimmune liver dysfunction, as well as glandular swelling." (PMID 34641948, 2021). "CD4+CD25+ Treg cell transplantation suppresses the progression of arthritis." (PMID 32565847, 2020). "Additionally, in EAE and collagen-induced arthritis models, transfer of regulatory B cells, CD4 Tregs, or CD8 Tregs, prevents autoimmunity." (PMID 33319815, 2020). "In RA, tryptophan is the substrate of indoleamine-2,3-dioxygenase IDO2, which was demonstrated to be required for the activation of CD4+ Th cells, the production of pathogenic autoantibodies, and the subsequent development of arthritis in a KRN mouse model of arthritis." (PMID 32235564, 2020). "Similarly to WT mice, butyrate supplementation suppressed arthritis severity and CD4+IL-17+T cell frequency only in AhR-sufficient Mb1cre/+ mice but not in Ahrfl/−Mb1cre/+ mice." (PMID 32213346, 2020). "Previous studies have shown that infiltrating innate immune cells like macrophages and adaptive immune cells such as CD4+ T cells and B cells in sublining synovium contributes to arthritis pathogenesis, as elimination of macrophages, CD4+ T cells, or B cells prevents arthritis development." (PMID 33270017, 2020). "However, this is the first study to characterize other specific senescent biomarkers, such as CD57, PD1, NKG2D, hTERC, or p16 in CD4+CD28− cells from early arthritis patients." (PMID 33291545, 2020). "The reduced expression of Egr2 coupled with increased T-bet and Granzyme B expression in PD-1high CD4 T cells may serve as one of the molecular signatures for active arthritis." (PMID 32709717, 2020). "Furthermore, IL‐23R(GFP)+CD4+CCR6+ T cells are present at the site of inflammation during the early phases of arthritis." (PMID 31778214, 2020). "However, when the colonic immunophenotype of Ptpn2-haploinsufficient mice was compared with WT mice, the only significant difference was a mild increase in total and CD4+ T cells in Ptpn2+/– mice with established DSS-induced arthritis." (PMID 33055428, 2020). "On the one hand, in the early stage of arthritis, B cells, served as antigen-presenting cells, could present antigens to CD4 + T cells, and activate CD4+T cells to secrete IL-2 and IFN-γ in the synovial membrane." (PMID 32066378, 2020). "CCR7 positive cells were decreased after improvement and positively associated with blood leukocyte levels, and CD4+CCR7+ and CD8+CCR7+ in whole PBL, CD4+CD62L- and CD8+CD62L- in lymphocytes population were correlated to the presence of arthritis symptoms of BD." (PMID 31614573, 2019). "Autoreactive CD4+ T cells are required for the induction of CIA, synovial proteins are subjected to PAD-induced citrullination and an association of anti-CII antibodies and ACPA to the development of arthritis has been described." (PMID 30837986, 2019). "In addition, the immunologic changes of high levels of some cytokines (IL1, IL-10, TNF-α, and IL-17) and high CD4+/CD8+ T cell ratio are detected in arthritis and osteoarthritis samples." (PMID 31842790, 2019). "Similarly, AhR deficiency restricted to B cells impairs IL-10+CD19+CD21hiCD24hiBreg differentiation and function, resulting in an increase of IFNγ and IL-17-expressing CD4+ T cells, a decrease in Tregs, and the development of an exacerbated arthritis." (PMID 31722204, 2019). "Therefore, in fresh blood from a newly recruited cohort of early arthritis patients (Cohort A) we compared receptor expression amongst TN, CM, and EM CD4+ T cells." (PMID 31333666, 2019).